TMEM131 (transmembrane protein 131)
Description:
Collagen binding transmembrane protein involved in collagen secretion by recruiting the ER-to-Golgi transport complex TRAPPIII. May play a role in the immune response to viral infection.
Synonyms: KIAA0257; RW1; CC28; YR-23; PRO1048
Tractability: Antibody: UniProt predicts a signal peptide or a membrane-spanning region. PROTAC: ubiquitination databases record sites on it; its protein half-life has been measured.
Gene: Protein-coding gene on chromosome 2 (97,756,333 to 97,996,226, reverse strand). Ensembl gene ENSG00000075568.
Subcellular location: Membrane
Subcellular location (Human Protein Atlas): Intermediate filaments; Vesicles
Gene Ontology:
Molecular function: collagen binding
Biological process: collagen biosynthetic process
Cellular component: membrane
Genetic constraint (gnomAD): Loss-of-function variants: 48 observed, 163.14 expected, observed/expected ratio (o/e) 0.29, 90% interval 0.23 to 0.37. The upper end of that interval is the gene's LOEUF score, 0.37, which puts it in group 1 of 6, group 1 being the genes least tolerant of losing a copy. Missense variants: 1,810 observed, 2,036 expected, observed/expected ratio (o/e) 0.89, 90% interval 0.85 to 0.92. Synonymous variants: 752 observed, 753.37 expected, observed/expected ratio (o/e) 1, 90% interval 0.94 to 1.06.
Homologues: Orthologues: chimpanzee TMEM131 (99% identical), macaque TMEM131 (99% identical), dog TMEM131 (95% identical), rabbit TMEM131 (95% identical), pig TMEM131 (94% identical), guinea pig TMEM131 (93% identical), mouse Tmem131 (90% identical), rat Tmem131 (89% identical), tropical clawed frog tmem131 (70% identical), zebrafish tmem131 (59% identical), Caenorhabditis elegans tmem-131 (22% identical), Drosophila melanogaster Tmem131 (22% identical). Paralogues in human: TMEM131L (20% identical).
Diseases named in the same sentence as TMEM131 in open-access papers:
TMEM131 is named in the same sentence as 5 diseases in open-access papers, as found by Europe PMC text mining. Sharing a sentence is not in itself a finding about the gene and the disease. The quoted sentences say what the papers report.
COVID-19 (1 paper, 2025). A disease caused by infection with severe acute respiratory syndrome coronavirus 2. "The hypermethylated genes with the lowest p values for hospitalized COVID-19 patients at inclusion (T1) vs. at 6 weeks post-inclusion (T2) were PARP9, ABCA1, MX1, OAS1, ARID5B, and the hypomethylated genes included TMEM131, ROCK1, IFNGR1, CFAP61, VRK2, and C6orf138." (PMID 41227320, 2025).
endometriosis (1 paper, 2025). The growth of functional endometrial tissue in anatomic sites outside the uterine body. "Through this analysis, we identified 42 genome-wide significant (5 × 10−8) genetic variants significantly associated with endometriosis, 6 of which were not reported previously: ABHD1/2p23.3, TMEM131/2q11.2, XRCC4/5q14.2, PPP1R9A/7q21.3, XKR6/8p23.1, and TRPS1/8p23.3." (PMID 40262193, 2025).
cancer (1 paper, 2021). A tumor composed of atypical neoplastic, often pleomorphic cells that invade other tissues. "Finally, TMEM131 and DARS genes were identified in this study whose roles have never been interrogated in any kind of cancer, neither as a biomarker nor curative target." (PMID 34249670, 2021).
TMEM131 also shares sentences with these, for which no sentence is quoted: endocarditis (1 paper); tumour (1).